CDH11 (cadherin 11)
Description:
Cadherins are calcium-dependent cell adhesion proteins. They preferentially interact with themselves in a homophilic manner in connecting cells; cadherins may thus contribute to the sorting of heterogeneous cell types. Required for proper focal adhesion assembly. Involved in the regulation of cell migration.
Synonyms: OB; CAD11; CDHOB; ESWS; OSF-4; TBHS2
Tractability: Antibody: its Gene Ontology location is reachable by antibodies, with high confidence; UniProt places it where antibodies can reach, with medium confidence; UniProt predicts a signal peptide or a membrane-spanning region. PROTAC: ubiquitination databases record sites on it; its protein half-life has been measured.
Gene: Protein-coding gene on chromosome 16 (64,943,753 to 65,126,112, reverse strand). Ensembl gene ENSG00000140937.
Subcellular location: Cell membrane
Pathways (Reactome):
Cell-Cell communication: Activation of STAT3 by cadherin engagement; Adherens junctions interactions; CDH11 homotypic and heterotypic interactions; Regulation of CDH11 function; Regulation of CDH11 gene transcription; Regulation of CDH11 mRNA translation by microRNAs; SRC activates STAT3 in a quantitative manner, through Cadherin-11 (CDH11), RAC1 and gp130 (IL6ST)
Gene Ontology:
Molecular function: beta-catenin binding; cadherin binding; calcium ion binding
Biological process: cell-substrate adhesion; focal adhesion assembly; negative regulation of cell migration; adherens junction organization; aortic valve formation; calcium-dependent cell-cell adhesion; cell adhesion; cell migration; cell morphogenesis; cell-cell adhesion mediated by cadherin; cell-cell junction assembly; ossification; skeletal system development; cell-cell adhesion; homophilic cell-cell adhesion; modulation of chemical synaptic transmission; skin development
Cellular component: extracellular exosome; adherens junction; catenin complex; extracellular region; plasma membrane; cytoplasm; glutamatergic synapse; membrane; Schaffer collateral - CA1 synapse; synapse
Genetic constraint (gnomAD): Loss-of-function variants: 8 observed, 57.98 expected, observed/expected ratio (o/e) 0.14, 90% interval 0.08 to 0.25. The upper end of that interval is the gene's LOEUF score, 0.25, which puts it in group 1 of 6, group 1 being the genes least tolerant of losing a copy. Missense variants: 797 observed, 991.69 expected, observed/expected ratio (o/e) 0.8, 90% interval 0.76 to 0.85. Synonymous variants: 372 observed, 384.79 expected, observed/expected ratio (o/e) 0.97, 90% interval 0.89 to 1.05.
Gene-disease validity (ClinGen):
ClinGen rates the evidence that CDH11 causes each of these diseases.
Elsahy-Waters syndrome (autosomal recessive): Definitive.
Teebi hypertelorism syndrome 2 (autosomal dominant): Moderate.
Cancer hallmarks: escaping programmed cell death (suppresses); invasion and metastasis (suppresses)
Homologues: Orthologues: chimpanzee CDH11 (99% identical), macaque CDH11 (99% identical), pig CDH11 (99% identical), rabbit CDH11 (99% identical), dog CDH11 (98% identical), rat Cdh11 (98% identical), mouse Cdh11 (97% identical), tropical clawed frog cdh11 (83% identical), zebrafish cdh11 (76% identical). Paralogues in human: CDH8 (66% identical), CDH18 (57% identical), CDH10 (57% identical), CDH7 (56% identical), CDH6 (56% identical), CDH20 (56% identical), CDH24 (55% identical), CDH12 (55% identical), CDH9 (55% identical), CDH22 (50% identical), CDH19 (44% identical), CDH5 (39% identical), and 21 more.
Diseases named in the same sentence as CDH11 in open-access papers:
CDH11 is named in the same sentence as 150 diseases in open-access papers, as found by Europe PMC text mining. Sharing a sentence is not in itself a finding about the gene and the disease. The quoted sentences say what the papers report.
breast carcinoma (61 papers, 2005 to 2025). "CDH11 expression in malignancies e.g. breast cancer is associated with poor outcome and has been also reported to promote a pro-invasive behavior in synovial fibroblasts, rendering CDH11 an attractive target for therapeutic intervention." (PMID 40118917, 2025). "CDH11 has been found to be implicated in the development of various malignancies, such as gastric cancer, osteosarcoma, and breast cancer." (PMID 40387410, 2025). "Increased CDH11 expression in breast cancer has been associated with poor prognosis and lower overall survival rates." (PMID 37558205, 2023). "Several proteins overexpressed in bone-seeking breast cancer cells were associated with increased migration and invasiveness in bone metastasis, including Osteoactvin, Cadherin-11, MMP-9 and CXCR4." (PMID 32226538, 2020). "Cadherin 11 (CDH11) is overexpressed in invasive breast cancer cells and implicated in distant bone metastases in several cancers." (PMID 30691241, 2019). "Collectively, we showed that elevated CDH11 is associated with breast cancer metastatic and CSC-like phenotypes, and its monospecific antibody targeting is a putative effective metastasis-limiting therapeutic option for treatment of metastatic breast cancer." (PMID 31248373, 2019). "To determine which member of ILF3 family was involved in the regulation of CDH11 expression, we examined CDH11 expression by lentivirally transducing breast cancer cells with expression vectors encoding NF90a, NF90b, NF110a or NF110b." (PMID 29296180, 2017). "CDH11 over-expression is associated with poor recurrence-free survival in breast cancer, and depletion of its transcription factor HOXC8 resulted in fewer metastases in animal models." (PMID 25686838, 2015). "Both high HOXC8 and CDH11 expression were significantly associated with poor recurrence-free survival rate of breast cancer patients (P = 0.002 and 0.041 respectively)." (PMID 24810778, 2014). "Aberrant expression of cadherin-11 in malignant cells, including breast cancer and prostate cancer, is associated with a more invasive and metastatic phenotype." (PMID 24917820, 2014). "Accordingly, the expression of cadherin-11 and N-cadherin and the loss of expression of E-cadherin confers a mesenchymal and invasive phenotype in breast cancer and other cancer cell lines." (PMID 24917820, 2014). "To do so, we first assessed the association between HOXC8 and CDH11 mRNA expression in breast tumors using microarray data of 414 breast cancer patients obtained from the Gene Expression Omnibus (GEO)." (PMID 24810778, 2014). "Indeed, CDH11 has been found to be expressed in most invasive breast cancer cell lines and has been proposed as a hallmark of invasiveness." (PMID 37558205, 2023). "To determine whether increased VE-cadherin expression in TCs is responsible for the downregulation of E-cadherin and cadherin-11, we transduced breast cancer cell lines with a VE-cadherin–GFP-encoding lentiviral vector." (PMID 32752204, 2020). "Later studies showed that HOXC8 is involved in breast cancer progression by either transcriptionally upregulating cadherin-11 expression or acting as a transcriptional repressor of the tumor suppressor Embigin." (PMID 40701951, 2025). "Previously, we have shown that HOXC8 acts as a transcriptional activator to promote expression of CDH11 in basal-like breast cancer cells leading to increased anchorage-independent cell growth, migration and invasion." (PMID 40701951, 2025). "In breast cancer, CDH11 is reportedly involved in many important biological processes by regulating the synthesis of ECM components and affecting tissue mechanical properties and contractile function." (PMID 41263259, 2025). "Inhibition of CDH11 has also been reported to inhibit tumor growth by suppressing the expression of β‐catenin and vimentin in mouse models of breast cancer." (PMID 41263259, 2025).
breast carcinoma (continued). "In vitro, overexpression of CDH11 in non‐metastatic breast cancer cell line MCF‐7 dramatically promotes cell migration and invasion potential." (PMID 37558205, 2023). "Conversely, 87.5% (63/72) of nuclear CDH11‐positive breast cancer patient samples were also positive for nuclear β‐catenin." (PMID 37558205, 2023). "In agreement with the larger multi‐tumor array, the percentage of CDH11+ cells in these two tumor arrays was highly similar (breast cancer TMA: % CDH11+ cells = 66.6, n = 219 vs. multiple tissue TMA: %CDH11+ cells = 65.8, n = 6)." (PMID 37558205, 2023). "Breast cancer is the most common cancer diagnosed globally and the increased CDH11 expression detected in TNBC correlates with malignant breast cancer and worse survival rates." (PMID 37558205, 2023). "The promotive effect of CDH11 expression in the metastasis of human cancers has been discovered in prostate cancer and early luminal breast cancer." (PMID 37013637, 2023). "CDH11 has been reported to promote the invasion and metastasis of prostate cancer and breast cancer." (PMID 37013637, 2023). "Remarkably, the vast majority of breast cancer samples exhibited nuclear β‐catenin (86.3%, or 63/73) and nuclear CDH11 (98.6%, or 72/73)." (PMID 37558205, 2023). "Collectively, these clinical data prompted us to examine the biological functions of nuclear CDH11 in breast cancer more closely." (PMID 37558205, 2023). "In particular, CDH11 was involved in the maintenance of high endogenous Rac activity and cytoskeletal reorganization in migratory breast cancer cells." (PMID 36315446, 2022). "Over half of the CpG sites of CDH11 presented high levels of methylation and relevance to breast cancer." (PMID 36315446, 2022). "To this end, we first characterized the expression of different cadherins (E-cadherin, N-cadherin, cadherin-11, and VE-cadherin) in a panel of breast cancer cell lines with different degrees of aggressiveness." (PMID 32752204, 2020). "In breast cancer, CDH11 enhances the ability of cancer cells to metastasize and invade, while blocking it inhibits the process of EMT phenotype." (PMID 32685527, 2020). "These new data highlight the mechanism by which CDH11 act on cancer cell migration and give new insights into CAF-S1-mediated CDH11 function on cancer cell metastatic spread in luminal breast cancer." (PMID 32665033, 2020). "The four TSGs: CBLC, CDH11, LZTR1, and TET2 previously shown to be most frequently mutated in 1KGP were also observed to display changes in ASE in breast cancer." (PMID 32064050, 2020). "Data was obtained from database GSE9586 and demonstrated that CDH11 mRNA level was prominently elevated in the metastatic breast cancer cells along with vimentin, CTNNB1 (β-catenin) as compared to E-cad (CDH1)." (PMID 31248373, 2019). "Conversely, the expression of CDH11 has been reported to activate tumor cells such as breast cancer." (PMID 30828336, 2019). "As a sequela, in the present study, we elucidated on the involvement of CDH11 in breast cancer metastasis, its epigenetic modulation, and its mechanistic undertone." (PMID 31248373, 2019). "In the present study, we demonstrated that high CDH11 expression positively correlates with poor prognosis in the more aggressive breast cancers subtypes, namely BL and TNBC subtypes." (PMID 30691241, 2019). "Another study showed that increased expression of CDH11 is characteristic of enhanced invasiveness in breast cancer cell lines, in vitro." (PMID 30691241, 2019). "Using the METABRIC-Breast Cancer (IlluminaHiSeq) cohort dataset (n = 1904), we investigated the correlation between CDH11 and several components of the WNT signalling pathway in the TNBC subgroup." (PMID 30691241, 2019). "Their work suggested the expression of cadherin 11 (CDH11) was inversely correlated with that of suppressors of metastasis in breast cancer." (PMID 31248373, 2019).
breast carcinoma (continued). "We demonstrated that compared to the untreated control, treatment with 1 mg/mL anti-CDH11 antibody significantly repressed the motility of the metastatic breast cancer cell lines, MCF7 (p < 0.05) and MDA-MB-231 (p < 0.001)." (PMID 31248373, 2019). "Compared to untreated breast cancer cells, treated breast cancer cells increased their expression of osteoblast cadherin CDH11, RUNX2, osteonectin (SPARC), the bone matrix-remodeling protein periostin, as well as a defined set of “bone-related genes”." (PMID 29867053, 2018). "Taken together, these data indicated that all ILF3 family members were involved in the regulation of CDH11 expression in breast cancer cells." (PMID 29296180, 2017). "In summary, all our data together demonstrated that LF3 and HOXC8 co-regulated CDH11 transcription in breast cancer cells and promoted the proliferation and migration of breast cancer cells by facilitating CDH11 expression in breast cancer cells." (PMID 29296180, 2017). "More importantly, high expression of CDH11, ILF3 and HOXC8 is linked to poor distant metastasis-free survival (DMFS) for breast cancer patients." (PMID 29296180, 2017). "Taken together, our study demonstrated that ILF3 was involved in HOXC8-regulated CDH11 transcription in breast cancer cells." (PMID 29296180, 2017). "Cadherin 11 (CDH11) expression is detected only in invasive breast cancer cells and aggressive breast cancer specimens." (PMID 29296180, 2017). "CDH11 expression has been detected in multiple types of cancer including breast cancer, prostate cancer, colon cancer, gastric cancer, renal cell carcinoma, and osteosarcoma." (PMID 29296180, 2017). "Taken together, these data indicated that ILF3 interacted with HOXC8 in CDH11-expressing breast cancer cell lines." (PMID 29296180, 2017). "We previously reported that Homeobox C8 (HOXC8) acts as a transcription factor to induce CDH11 expression in breast cancer cells." (PMID 29296180, 2017). "We further show that ILF3 promotes proliferation and migration, at least partially, by facilitating CDH11 expression in breast cancer cells." (PMID 29296180, 2017). "Here, we report that interleukin enhancer binding factor 3 (ILF3) interacts with Homeobox C8 (HOXC8) to activate CDH11 transcription in breast cancer cells." (PMID 29296180, 2017). "Previous studies have reported an increased expression of HOXC8 during breast cancer progression that can induce metastasis through direct regulation of CDH11 and EMB genes." (PMID 28202042, 2017). "Together, these observations indicated that ILF3 and HOXC8 formed a protein complex to co-activate CDH11 transcription in breast cancer cells." (PMID 29296180, 2017). "MTT assays indicated that ILF3-knockdown breast cancer cells displayed an impaired capability for proliferation, which was almost restored by ectopically expressing CDH11 in the ILF3-knockdown cells." (PMID 29296180, 2017). "Taken together, these data indicated that ILF3 bound to CDH11 promoter at the sites of nucleotides –2982 ~ –2978 and –2602 ~ 2598 and functioned as a transcriptional activator to regulate CDH11 transcription in breast cancer cell lines." (PMID 29296180, 2017). "CDH11 has been reported to be overexpressed in aggressive breast cancers and bone metastatic breast cancer cells." (PMID 27806311, 2016). "The breast carcinoma cells increased spreading, microfilament bundle and focal adhesion assembly, and increased the extent of cadherin 11-mediated adherens junctions." (PMID 25623282, 2015). "It has been reported that HOXC8 takes part in a number of genes regulation in mouse fibroblasts, and our previous study also showed that HOXC8 promotes breast cancer cell migration and metastasis through activating cadherin-11 transcription." (PMID 26090721, 2015). "Previously we reported that HOXC8 plays an important role in breast tumorigenesis, and acts as a transcription factor in cadherin-11 transcription in breast cancer cells." (PMID 26090721, 2015).
breast carcinoma (continued). "Here, we show that CDH11 is transcriptionally controlled by homeobox C8 (HOXC8) in human breast cancer cells." (PMID 24810778, 2014). "To understand the molecular mechanism mediating CDH11 expression in invasive breast cancer cells, we showed that knockdown of HOXC8 led to the reduction of CDH11 expression." (PMID 24810778, 2014). "Our analysis of all published human breast cancer microarray datasets as well as our immunohistochemical studies showed that increased CDH11 is an early event in breast cancer progression." (PMID 24681547, 2014). "Forced expression of CDH11 has been shown to be sufficient to induce breast cancer cell migration and metastasis." (PMID 24810778, 2014). "Our reasoning is apparently supported by the observation that ectopically expressing CDH11 restored various tumorigenic events diminished in HOXC8-knockdown breast cancer cells." (PMID 24810778, 2014). "Kaplan-Meier analysis further shows that both high HOXC8 and CDH11 expression correlate with poor recurrence-free survival of breast cancer patients." (PMID 24810778, 2014). "The current work also demonstrates the critical role that CDH11 plays in tumorigenesis of aggressive, basal or mesenchymal-like breast cancer." (PMID 24681547, 2014). "Cell-cell adhesion molecule cadherin-11(CDH11) is preferentially expressed in basal-like breast cancer cells and facilitates breast cancer cell migration by promoting small GTPase Rac activity." (PMID 24810778, 2014). "Subsequently, we performed survival analysis (Kaplan-Meier method, log-rank test) to assess the potential correlation between HOXC8/CDH11 expression and recurrence-free survival of breast cancer patients." (PMID 24810778, 2014). "CDH11 over-expression in a subset of DCIS indicates it as an early event in breast cancer development." (PMID 24681547, 2014). "Here, we show that enforcing HOXC8 expression significantly upregulates CDH11 expression in breast cancer cells." (PMID 24810778, 2014). "Together, our study suggests that HOXC8 promotes breast tumorigenesis by maintaining high level of CDH11 expression in breast cancer cells." (PMID 24810778, 2014). "CDH11 expressing basal-like breast carcinomas and other CDH11 expressing malignancies exhibit poor prognosis." (PMID 24681547, 2014). "It is plausible that CDH11 expression in breast cancer is a component of the EMT that allows cells to progress and metastasize." (PMID 24681547, 2014). "CDH11 level was apparently correlated with HOXC8 expression because breast cancer cell lines with CDH11 expression all displayed relatively higher HOXC8 level compared with those with little or no detectable CDH11." (PMID 24810778, 2014). "The initial objective of this study is to understand how CDH11 expression is regulated in breast cancer cells." (PMID 24810778, 2014). "Our data indicates that CDH11 is an important factor in malignant progression and is a promising therapeutic target in poor prognosis breast cancers and other CDH11 expressing malignancies such as glioblastoma, and perhaps androgen-independent prostate cancer." (PMID 24681547, 2014). "Reduction of CDH11 in MDA-MB-231 breast cancer cells with siRNA or shRNA significantly decreased growth, colony formation and migration." (PMID 24681547, 2014). "MDA-MB-231 cells, a mesenchymal-like breast cancer cell line that expresses cadherin-11, have undetectable levels of other cadherins and low levels of activated β-catenin." (PMID 19274078, 2009). "Furthermore, it has been discovered that the transcription factor homology box C8 (HOXC8) specifically binds to the promoter region of the CDH11 gene and maintains high levels of CDH11 gene expression in breast cancer." (PMID 40362031, 2025). "Indeed, a dual N-Cadherin and Cadherin-11 targeting antibody has been shown to reduce breast cancer metastasis." (PMID 38473331, 2024).